HOXA9 (homeobox A9)
Diseases named in the same sentence as HOXA9 in open-access papers (continued):
Sharing a sentence is not in itself a finding about the gene and the disease.
leukemia (continued). "For instance, JMJD1C functions as a co-activator for Runx1-Runx1T1 in acute myeloid leukemia cell lines and for HoxA9 in mixed lineage leukemia-AF9 and HoxA9-driven leukemia." (PMID 27649575, 2016). "While HOXA9 is an established oncogene in the context of leukemia, our study is the first to clearly demonstrate the oncogenic potential of HOXA9 in gliomas." (PMID 25762636, 2015). "Our data in GBM also identified novel HOXA9 target genes involved in cell proliferation and cytoskeletal organization pathways, which have previously been identified as HOXA9 downstream effectors in leukemia." (PMID 25762636, 2015). "Acceleration of Meis-HoxA9-induced leukemia on a Prep1-hypomorphic background has also been reported." (PMID 26285139, 2015). "Globally, our data show that HOXA9 increases cell viability, invasion, and resistance to cell death in GBM, establishing a good parallel with HOXA9 functions observed in leukemia models." (PMID 25762636, 2015). "PC4 and SF2 interacting protein 1 (PSIP1)/p75, also known as LEDGF, whose PWWP domain binds to H3K36me3, interacts with MLL and tethers MLL fusion proteins to HOXA9 in leukaemias." (PMID 25056311, 2014). "SYC-522 significantly inhibited methylation at H3K79, but not H3K4 or H3K27, and decreased the expression of two important leukemia-relevant genes, HOXA9 and MEIS1, by more than 50%." (PMID 24858818, 2014). "PSIP1, and particularly its PWWP domain, is known to be required for MLL1-mediated leukemogenesis, and for targeting MLL1 fusion partners leading to uncontrolled expression of HOXA9 in leukemia." (PMID 25056311, 2014). "In primary hematopoietic progenitors, Meis1 overexpression is unable on its own to transform, but cooperates in the oncogenic activity by accelerating HoxA9-induced leukemia." (PMID 24809472, 2014). "Our results identify a mechanism for increased and sustained CDX4 transcription in leukemias co-overexpressing HoxA9 and HoxA10 in combination with constitutive activation of Shp2." (PMID 25531430, 2014). "Using Flt3 knock out mice, we previously found that leukemias induced by the retroviral transduction of Hoxa9 and Meis1, which recapitulate many features of MLL-rearranged myeloid leukemias, are Flt3 independent." (PMID 23977266, 2013). "Compelling evidence links recruitment of the histone methyltransferase DOT1L to transcriptional activation of oncogenes such as HOXA9 in MLL-R leukemia." (PMID 23847761, 2013). "EPZ004777 displayed selective killing of MLL-R leukemia cell lines and suppressed expression of the HOXA9 and MEIS1 oncogenes, consistent with the proposed role of the enzyme target." (PMID 23847761, 2013). "Excessive expression of FLT3 in MLL-rearranged leukemias results from direct transcriptional activation by HOXA9 and MEIS1 and post-transcriptional regulation by miR-150, a microRNA whose level is repressed by MLL fusion genes." (PMID 23977266, 2013). "We show for the first time that maintenance of Bcl-2 expression is critical for HoxA9-dependent immortalization and influences the latency of HoxA9-dependent leukemia." (PMID 24177192, 2013). "The involvement of homeobox genes as partners of NUP98 is of particular interest given the growing evidence linking Hox genes, particularly members of the 5′-located members of the HOXA cluster, such as HOXA9, to leukemia." (PMID 17712416, 2007). "Overexpression of several Hox genes such as Hoxa9 induce leukemia reminiscent of mixed lineage leukemia (MLL)." (PMID 17183676, 2006). "Importantly, forced expression of Hoxa9 in combination with the co‐factors Meis1 or Pbx3 alone was sufficient to induce leukemia, establishing those genes as central functional drivers in KMT2A‐rearranged leukemia by shaping the leukemic enhancer landscape." (PMID 39887730, 2026).
leukemia (continued). "Cell line/primary blasts/in vivo (THP-1, U937, ER-HoxA9 GMP Cell Lines, the HoxA9 + Meis1 or MLL/AF9 primary leukemia cells.Subcutaneous xenograft tumor mice models, disseminated intravenous xenograft leukemia mice models, patient AML sample engrafted (PDX) mice)." (PMID 41590345, 2026). "This is consistent with our evidence that HOXA9 could restore the FLT3 expression in RBM5 null leukemia cells." (PMID 38216972, 2024). "Notably, the overexpression of HOXA9 significantly restored the cell expansion in the RBM5 sgRNA-treated leukemia cells, similar to the extent of RBM5 overexpression." (PMID 38216972, 2024). "HOXA9 transcription is dependent on DOT1L-mediated H3K79 methylation in KMT2A-r leukemia." (PMID 38601080, 2024). "However, BCL2 and HOXA9 overexpression inhibited miR-182-induced anti-leukemia activity to some extent, suggesting that there were other targets regulated by miR-182 in AML." (PMID 36593968, 2023). "In concordance with our findings, a recent protein interactome study of cellular and chromatin-associated HOXA9 in AML supports the hypothesis that a block in myeloid differentiation is an active and crucial process for the maintenance of leukemia." (PMID 37735473, 2023). "High-level expression of IRX3 is frequent in human leukemia, is sufficient for immortalization of murine hematopoietic stem and progenitor cells, and when co-expressed with Hoxa9 in a murine model substantially deepens the level of differentiation block observed in the resulting AMLs." (PMID 37539037, 2023). "Notably, overexpression of HOXA9 has been identified in several specific leukemia subtypes, including the MLL-r, NPM1c, EZH2-mutant, and NUP98-fusion subtypes." (PMID 38016946, 2023). "Of interest, the HOXA9 broad H3K79me2 domain has several genes with known roles in leukemia." (PMID 36139405, 2022). "In line with this, MLL-AF4-driven leukemia is a distinct entity, with a unique gene expression profile showing significant overlap with stem cell programs and enhanced H3K79 methylation at known stem-cell associated genes such as HOXA9, MEIS1, and FLT3." (PMID 36307883, 2022). "We next turned our focus to early leukemia progression in a Hoxa9/Meis1-Ubiquitin-c-GFP (HA9M1) mouse model of AML, performing intravital imaging of the calvarium bone marrow between 1 and 3 days after transplanting 3 × 106 cells into non-irradiated recipients." (PMID 36424441, 2022). "In addition, there was evidence showing that miR-17 ~ 92 cluster contributed to the MEIS1/HOXA9-mediated transformation of MLL leukemia." (PMID 35536524, 2022). "Viral co-transduction of the MLL-AF4 targets HOXA9 and MEIS1 is sufficient to cause acute leukemia in mouse bone marrow progenitors, arguing that these transcription factors represent a major etiologic pathway in MLL-r leukemia." (PMID 34263728, 2021). "We identified that JDM‐7 downregulates the LSC self‐renewal gene HOXA9 in leukemia cells." (PMID 33289299, 2021). "The inhibition of the (H3K9)‐demethylase JMJD1C, on the other hand, causes only minor defects with respect to blood homeostasis and has a minor influence on the self‐renewal of the hematopoietic stem cells with a simultaneous reduction of LSC frequency in MLL‐AF9‐ and HOXA9‐driven leukemias." (PMID 33289299, 2021). "It is possible that the dependence of MLL-r, FLT3-ITD+ leukemia on FLT3-ITD expression may be due to HOXA9 requiring STAT5A and/or PBX3 and C/EBPA to cooperatively bind select target genes." (PMID 34263728, 2021). "Indeed, we observed a significant decrease in Meis1 and Hoxa9 expression in Δ10-DOT1L and I867A-DOT1L leukemia cells, comparable to the changes induced by complete loss of DOT1L (empty vector) or by DOT1L enzymatic inhibition (RCR-DOT1L)." (PMID 33562706, 2021). "(E) A model illustrating HOXA9-mediated pathogenesis in MLL fusion-mediated leukemia." (PMID 34310280, 2021). "NPMc+ and IDH2R140Q together activate the Hoxa9/Meis1 pathway to drive leukemia in mice." (PMID 34944812, 2021).
leukemia (continued). "Representative PCR gel results revealed three specific bands corresponding to HoxB5, HoxA9, and Meis1, indicating that these driving oncogenes were gnomically integrated into the leukemia cells and suggesting their involvement in leukemia generated in ML23 mice." (PMID 33602907, 2021). "Another study showed that in mixed lineage leukaemia (MLL)-rearranged leukaemia, miR-196b could directly target left HOXA9/MEIS1 oncogenes and FAS tumor suppressor." (PMID 33611311, 2021). "This additional MYC activity may be required to achieve sufficient leukemogenic ability, therefore MYC/HOXA9-transduced cells were able to induce leukemia in vivo." (PMID 34310280, 2021). "Furthermore, MLL-AF10 activated both the HOXA9 high and MYC high signature genes to induce leukemia while ectopic expression of HOXA9 and MYC synergistically induced leukemia." (PMID 34310280, 2021). "In addition, USF1 and USF2 synergistically regulate HOXA9 expression and leukemia survival in OCI-AML2." (PMID 33001025, 2020). "Interestingly, WNT6 and HOXA9 were also found to be co‐expressed in other cancer types, including leukemia, testicular germ cell tumor, melanoma, and CHOL." (PMID 31923345, 2020). "The presence of PBX3 and MEIS1 increases HOXA9-induced leukemia." (PMID 33402862, 2020). "Thus, excessive HOXA9 expression has emerged as a critical mechanism of leukemia transformation in many hematopoietic malignancies." (PMID 33001025, 2020). "Moreover, WNT6 and HOXA9 were not only co‐expressed in glioma, but also in leukemia, a cancer type where the oncogenic roles of HOXA9 are well established, and also in TGCT, CHOL, and melanoma." (PMID 31923345, 2020). "However, our current understanding of HOXA9 regulation in leukemia is limited, hindering development of therapeutic strategies." (PMID 33001025, 2020). "USF2 depletion selectively downregulated HOXA9 expression in MLLr leukemia cells and impaired cell growth, which could be rescued by ectopic expression of HOXA9 and its partner MEIS1." (PMID 33001025, 2020). "Notably, the high expression of HOXA9 is sharply correlated with poor prognosis and outcome in human leukemia." (PMID 33001025, 2020). "Although a few regulators of HOXA9 in MLLr leukemia have been previously identified, to date a comprehensive CRISPR/Cas9 screen to unbiasedly identify novel upstream regulatory factors of HOXA9 has not been feasible owing to the lack of a reliable reporter cell line." (PMID 33001025, 2020). "USF2 is required to maintain HOXA9 expression in MLLr leukemia." (PMID 33001025, 2020). "USF1 and USF2 synergistically regulate HOXA9 expression in MLLr leukemia." (PMID 33001025, 2020). "The trimeric structure of HOXA9/MEIS1/PBX3 supports HOXA9-driven leukemia." (PMID 33402862, 2020). "The interaction between MEIS1 and HOXA9, for example, is known to be tumorigenic in leukemia." (PMID 32553107, 2020). "Importantly, the NUP98 translocations that occur in AML all share the N-terminus of the protein and are thought to initially lead to epigenetic dysregulation of different leukemia-associated genes including HOXA7, HOXA9, and HOXA10 in myeloid precursor cells." (PMID 31467532, 2019). "Using the RNA interference technique, HOXA9 has been shown to inhibit MLL rearrangement in MLL-rearranged leukemias, suggesting that targeting HOXA9 or its downstream signaling partners may present an effective therapeutic strategy." (PMID 31426381, 2019). "High expression of HOXA9 in leukemia blasts predicts adverse outcome in AML." (PMID 31681594, 2019). "Functionally, proliferation and survival are preferentially affected in HOXA9-induced leukemia." (PMID 31013831, 2019). "For example, HOXA9 was found to be overexpressed in leukemia, but downregulated in breast cancer." (PMID 31013831, 2019).
leukemia (continued). "Targeting the protein/protein interface is one strategy that has already been developed to target the HOX protein though its interaction with specific co-factors, since the interaction of HOXA9 with some cofactors is a key element for leukemia induction and aggressiveness." (PMID 31213012, 2019). "If HOXA9 could act alone to trigger leukemia, it requires cofactors to increase its propensity to induce leukemia." (PMID 31213012, 2019). "Likewise, the set of genes anti-correlated with the LSC maintenance program (i.e., associated with differentiated leukemia cells, downstream of the LSC) was strongly repressed in Hoxa9/IRX3 versus Hoxa9/MTV AML cells." (PMID 29346763, 2018). "To determine whether co-expression of IRX3 influences leukemia cell differentiation in vivo, we transplanted Hoxa9/IRX3 and Hoxa9/MTV double-transduced BM HSPCs into irradiated congenic recipients." (PMID 29346763, 2018). "Analysis of 8,954 protein-coding genes that passed threshold criteria (i.e., expression >0.5 reads per kilobase per million mapped reads [RPKM] in at least one sample) revealed that 197 were upregulated and 403 downregulated by at least 2-fold in Hoxa9/IRX3 versus Hoxa9/MTV leukemias." (PMID 29346763, 2018). "In vivo analyses, FOXC1 dramatically promoted the onset of symptomatic leukemia with HOXA9." (PMID 29552326, 2018). "Insertion of this domain into Hoxa9 impaired oncogenic potential for leukemia." (PMID 30154863, 2018). "Thus, the events documented after ZNF521 depletion, which in part resemble what has been previously observed in MLL-rearranged cells after loss of HOXA9, gave a further support that ZNF521 plays a critical role in MLL-fusion-mediated leukemia." (PMID 28412727, 2017). "In addition, the frequency of c-Kit-positive cells was higher for Hoxa9 and Meis1, and for Hoxa9 and hSYK, compared with Hoxa9 alone, suggesting a more immature phenotype of the developing leukemias." (PMID 28399410, 2017). "Thus, mitochondrial Fh1 is necessary for efficient LIC generation but is not required for their ability to efficiently propagate Meis1/Hoxa9-driven leukemia." (PMID 28202494, 2017). "Finally, Syk inhibition disrupts the identified regulatory loop, prolonging survival of mice with Hoxa9/Meis1-driven leukemia." (PMID 28399410, 2017). "Thus, we reveal a differential requirement for the mitochondrial TCA enzyme Fh1 in normal hematopoiesis and Meis1/Hoxa9-driven leukemia propagation." (PMID 28202494, 2017). "In addition, it was also shown to reduce the expression of MLL1 target genes such as HoxA9 and Meis1 in leukemia cell lines." (PMID 28182322, 2017). "Similarly, Hoxa9 enhances hematopoietic stem cell regeneration in vivo, ultimately leading to the development of leukemia, albeit with a long latency." (PMID 28399410, 2017). "Leukemias induced by the combination of Hoxa9 with hSYK or Hoxa9 with Meis1 were characterized by lower leukocyte counts and a more pronounced anemia compared with Hoxa9 alone." (PMID 28399410, 2017). "Interestingly, we found that all mice receiving GMPs co-transduced by BCR/ABL and Hoxa10 viruses also developed myeloid leukemias, although with longer latencies than leukemias induced by Hoxa9+BCR/ABL." (PMID 29228732, 2017). "Interestingly, the only mouse transplanted with Prmt1 knockdown cells that succumbed to leukemia re-expressed high levels of Prmt1 and Hoxa9, suggesting a high selective pressure against Prmt1 knockdown for leukemia development." (PMID 26766589, 2016). "Notably, a recent report also demonstrated that Crm1 binds to the HoxA9 and HoxA10 gene regions, both in human leukemia cell line and immortalized mouse embryonic fibroblast cell line." (PMID 26740045, 2016). "This includes HoxA9, and genes correlated with HOXA9 in human leukemia." (PMID 27242978, 2016).
leukemia (continued). "The MLL-AF9 fusion protein, which interacts with p-TEFb/DOT1l, is not capable of inducing leukemia in recipient mice when introduced into Hoxa9 deficient cells, while the cytoplasmic fusion MLL-GAS7 is capable of driving leukemia in cells deficient for either Hoxa9 or Hoxa7." (PMID 27007052, 2016). "The fact that HOXA9 transcriptomes were so distinct within GBM cells (U87MG, U251 and GBML18) and in immortalized astrocytes (hTERT/E6/E7) cells suggests that HOXA9 targets different genes in a cell-type dependent manner, which is in accordance with previous reports in leukemia models." (PMID 25762636, 2015). "In addition, in a previous gene expression study of human leukemia, HOXA9 emerged as one of the top 20 genes that distinguished AML from ALL." (PMID 24385825, 2013). "Thus, FLT3 expression was associated with HOXA5, HOXA7, HOXA9 and MEIS1 in human leukemia and this gene expression profile was confined to leukemia with either intermediate or unfavorable cytogenetics." (PMID 17712416, 2007). "The finding that HLF also correlated with HOXA7 and HOXA9 in human leukemia suggests that this gene also might be important for Hox induced cell transformation and development of leukemia." (PMID 17712416, 2007). "HOXA9 overexpression was also identified in many different leukemia subtypes, including onco-fusion proteins, NPM1c+, etc.; experimental validation of the target binding site and cellular function is interesting for understanding HOXA9’s role in other HOXA9-driven leukemia cells." (PMID 38016946, 2023). "Moreover, SCUBE1 could be an important target in AML and other types of leukemia due to its regulation by HOXA9, which is overexpressed in a broad range of leukemias." (PMID 37237303, 2023). "Moreover, we identified a different HOXA9-bound site distant from FLT3 in MLL-r leukemia cells." (PMID 38016946, 2023). "In addition to leukemia, HOXA9 overexpression is also observed in cases of colorectal cancer (CRC)." (PMID 35743243, 2022). "However, knockdown of FABP4 was able to promote survival in HOXA9/MEIS1-driven leukemia model mice." (PMID 36002858, 2022). "In addition to CRC, HOXA9 has been found to be overexpressed in breast cancer and leukemia." (PMID 35743243, 2022). "Indeed, SYK inhibition prolonged survival of mice with Hoxa9/Meis1-driven leukemia." (PMID 35216478, 2022). "Thus, MEF2C may activate expression of HOXA9 in non-KMT2Ar leukemias, while the role of MEF2D is restricted to KMT2Ar AML." (PMID 35301220, 2022). "Thus, simultaneously blocking multiple anti-apoptotic pathways may be required for efficient molecularly targeted therapy of HOXA9-expressing leukemia." (PMID 34310280, 2021). "It has also been already described that a Meis1 mutated in its HR2 domain could not cooperate with Hoxa9 in colony-forming assays or in in vivo leukemia assays." (PMID 34698191, 2021). "Moreover, overexpression of HOXA9 is observed in many non-MLL fusion-mediated leukemias such as those with NPM1 mutation and NUP98 fusion and is associated with poor prognosis." (PMID 34310280, 2021). "Finally, we performed gene expression studies in MLL-AF9 and MLL-AF6 transformed bone marrow cells and found that genes highly relevant to MLL leukemia (Hoxa5, Hoxa9, Hoxa10, Meis1, and Mef2C) were expressed at much lower levels in the ΔSET Ash1l versus WT Ash1l cells." (PMID 33990599, 2021). "Moreover, changes to MEIS/HOXB13 transcriptional regulation or interaction by HOXB13 mutations could enable MEIS proteins to pair with HOXA9 or HOXA10 to drive oncogenesis and progression, such as in leukemia or ovarian cancer." (PMID 32553107, 2020). "Finally, HOXA9, which is frequently overexpressed in acute myeloid leukemia and may promote leukemia through epigenetic landscape remodeling, was up-regulated." (PMID 33226961, 2020).